UCA1 (urothelial cancer associated 1)
Diseases named in the same sentence as UCA1 in open-access papers (continued):
Sharing a sentence is not in itself a finding about the gene and the disease.
bladder cancer (continued). "In addition, in vivo studies demonstrated that UCA1 was involved in bladder cancer progression, and the knockdown of UCA1 inhibited growth, migration, and invasion in bladder cancer cells." (PMID 36899946, 2023). "In addition, studies which aimed to understand the roles of lncRNAs in the metabolism of bladder cancer cells found that UCA1 promotes mitochondrial function in bladder cancer via the miR-195/ADP-ribosylation factor-like 2 (ARL2) signaling pathway." (PMID 36605618, 2023). "The role of UCA1 in bladder cancer tumorigenesis has been reported in various studies." (PMID 36685879, 2022). "However, bladder cancer is where UCA1 is highly expressed; UCA1 has been reported to be upregulated in CRC cells to inhibit apoptosis and develop tumorigenesis." (PMID 36699052, 2022). "UCA1 is among the well-studied and good candidates for bladder cancer biomarkers." (PMID 36685879, 2022). "Similarly, UCA1 increases the cisplatin resistance of bladder cancer cells by enhancing Wnt6 expression, and thus represents a potential target to overcome chemoresistance in bladder cancer." (PMID 33565716, 2021). "UCA1 was first identified in bladder cancer and is considered a novel oncogenic lncRNA." (PMID 34527584, 2021). "UCA1 upregulation promotes cell survival in bladder cancer during treatment with cisplatin." (PMID 34425750, 2021). "Notably, UCA1 can also increase cisplatin resistance of bladder cancer cells by activating Wnt signaling in a Wnt6-dependent manner." (PMID 33777227, 2021). "In addition, UCA1 promotes migration and invasion of bladder cancer cells via the has-miR-145/ZEB1/2/FSCN1 pathway." (PMID 34238213, 2021). "UCA1 promotes bladder cancer cell migration and invasion through miR-145 targeting." (PMID 34733326, 2021). "The elevated UCA1 upregulated ATG7 in bladder cancers by sponging miR-582-5p." (PMID 33050642, 2020). "Moreover, it has been shown that the UCA1 increases drug resistance through WNT signaling pathway in bladder cancer." (PMID 31956395, 2020). "The hypoxic exosomes facilitated bladder cancer progression through EMT both in vivo and in vitro, which may be caused by UCA1/miR-582-5p/ATG7-mediated autophagy." (PMID 33050642, 2020). "The lncRNA UCA1 was found to be overexpressed in bladder cancers." (PMID 33050642, 2020). "Moreover, they introduced (UCA1-201, UCA1-203, MALAT1, and LINC00355) as a diagnostic panel of lncRNAs in bladder cancer." (PMID 31956395, 2020). "Moreover, serum-derived exosomes of bladder cancer patients showed a significantly higher level of lncRNA UCA1, and notably, the lncRNA UCA1 levels were positively correlated with HIF-1α expression." (PMID 32503591, 2020). "LncRNA urothelial carcinoma-associated 1 (UCA1) interferes the negative regulation of GLS2 mRNA by miR-16, upregulating GLS2 expression to promote glutaminolysis, inhibit ROS production and protect cells from oxidative toxicity in bladder cancer 95-97." (PMID 32174794, 2020). "Similarly, frequent upregulation of UCA1 is observed in various cancers, including lung cancer, bladder cancer, gastric cancer, liver cancer, and colorectal cancer." (PMID 32733618, 2020). "UCA1 has been shown to increase mitochondrial function in bladder cancer cells." (PMID 33123468, 2020). "In addition, a number of studies have shown that UCA1 expression can be detected in tumors of bladder cancer patients, as well as in their urine, and exhibits tumor tissue specificity." (PMID 30940184, 2019). "Moreover, UCA1 increases cisplatin resistance by upregulating Wnt6 expression and suppressing cell apoptosis in bladder cancer." (PMID 31777598, 2019). "Moreover, UCA1 promotes mitochondrial function of bladder cancer via the miR-195/ARL2 signaling pathway." (PMID 30940776, 2019). "UCA1 was originally discovered to be overexpressed in bladder cancer." (PMID 31467637, 2019). "In bladder cancer, UCA1 could promote glycolysis by up-regulating hexokinase 2 through both activation of STAT3 and repression of miR-143." (PMID 30918102, 2019).
bladder cancer (continued). "Furthermore, after the transfection of pre-miR-1 or following the treatment of UCA1 shRNA, cell proliferation and motility decreased in bladder cancer cell lines in an AGO2-mediated manner." (PMID 31694571, 2019). "UCA1 is the first lncRNA that acknowledged in human bladder cancer." (PMID 31844718, 2019). "UCA1, a novel functional lncRNA which was first discovered in 2006 in human bladder cancer." (PMID 30918102, 2019). "Our study confirmed that BMP9 could up regulate the expression of UCA1 in an AKT-dependent pathway in bladder cancer cells." (PMID 29642505, 2018). "In the present study, we found that lncRNA UCA1 may play a critical role in the effect of BMP9 on bladder cancer cells." (PMID 29642505, 2018). "UCA1 mediates bladder cancer migration and invasion through the miR-145-ZEB1/2-fascin pathway." (PMID 29618386, 2018). "Therefore, UCA1 can be considered as a potential biomarker to assist in the diagnosis of bladder cancer." (PMID 29899709, 2018). "A link between UCA1 and the transcription factor CREB (cAMP response element-binding protein) was found in bladder cancer cells indicating that UCA1 might influence cell cycle regulation by activating CREB via PI3K–AKT pathway." (PMID 29389884, 2018). "For the diagnostic values, UCA1 expression profile achieved a combined AUC of 0.92, with sensitivity of 0.84 and specificity of 0.89 in distinguishing patients with bladder cancer from non-cancerous controls." (PMID 29899709, 2018). "In the case of bladder cancer, overexpression of lncRNA UCA1 was observed." (PMID 30441874, 2018). "UCA1 is also responsible for resistance of bladder cancer cells to cisplatin." (PMID 30441874, 2018). "Interestingly, lncRNA UCA1 is also detected in blood and urine samples from bladder cancer patients and is a useful circulating biomarker." (PMID 28969100, 2017). "Thus, we showed the utility of CRISPR/Cas9 in the modulation of lncRNA and verified the oncogenic role of UCA1 in bladder cancer." (PMID 28038452, 2017). "Several recent studies have also identified oncogenic functions of lncRNA UCA1 in various cancers such as bladder cancer, breast cancer, colorectal cancer, esophageal squamous cell carcinoma, gastric cancer, hepatocellular carcinoma, melanoma, ovarian cancer, and tongue squamous cell carcinoma." (PMID 28969100, 2017). "Furthermore, UCA1 remarkably increased expression of Wnt6 in human bladder cancer cell lines, and their expression was also positively correlated in vivo." (PMID 27713133, 2017). "Collectively, our data suggest that CRISPR/Cas9 technique can be used to down-modulate lncRNA expression, and urinary UCA1 may be used as a non-invasive marker for diagnosis of bladder cancer." (PMID 28038452, 2017). "In conclusion, our study first reported that CRISPR/Cas9 could be used to effectively suppress lncRNA level, and highlighted that UCA1 as an oncogene of bladder cancer." (PMID 28038452, 2017). "UCA1 lncRNA has been identified as a potential biomarker for bladder cancer." (PMID 28634418, 2017). "Further, many studies show that lncRNA UCA1 induces drug resistance in various cancers such as bladder cancer, ovarian cancer, breast cancer, lung cancer, gastric cancer, colorectal cancer, prostate cancer and CML, thereby greatly reducing the efficacy of cancer therapy." (PMID 28969100, 2017). "UCA1 promotes bladder cancer progression by targeting miR-1, miR-16 and miR-145." (PMID 27893417, 2017). "UCA1 has also been reported to be related to cisplatin resistance in bladder carcinoma." (PMID 29279851, 2017). "Notably, the chemoresistance of bladder cancer cells is increased by UCA1 through regulating the Wnt signaling." (PMID 27911863, 2017). "Finally, UCA1 promoted cisplatin resistance of bladder cancer cells by enhancing the expression of Wnt6 and activating Wnt signaling." (PMID 27713133, 2017).
bladder cancer (continued). "In fact, knockdown of lncRNA UCA1 by short interfering RNAs (siRNA) or short hairpin RNA (shRNA) has been shown to reverse drug resistance in various cancer cells such as bladder cancer, breast cancer, lung cancer, gastric cancer, colorectal cancer, prostate cancer, CML, ovarian cancer." (PMID 28969100, 2017). "Collectively, these data indicate UCA1 may act as not only an intracellular hypoxia-responsive lncRNA but also an exosomal hypoxia-responsive lncRNA in bladder cancer." (PMID 28841829, 2017). "UCA1 can be detected in urine samples of bladder cancer patients, mostly in the cellular sediments." (PMID 28634418, 2017). "The lncRNA UCA1 was first cloned and identified from bladder cancer cell line BLZ-211." (PMID 28969100, 2017). "An AUC of 0.88 (95% CI, 0.85-0.91), with pooled SEN of 0.81 (95% CI, 0.75-0.86) and SPE of 0.86 (95% CI, 0.73-0.93) showed that UCA1 in voided urine sediment may be a promising biomarker to discriminate bladder cancer patients from normal bladder." (PMID 28415640, 2017). "UCA1 induces EMT in bladder cancer cells by upregulating the expression of ZEB1 and ZEB2." (PMID 28430163, 2017). "Importantly, UCA1 has also been identified as a hypoxia-responsive lncRNA that can promote the proliferation, migration, and invasion of bladder cancer cells under hypoxia." (PMID 28841829, 2017). "These in vitro results indicated that UCA1 acted as an oncogenic lncRNA in bladder cancer." (PMID 28038452, 2017). "In bladder cancer, UCA1 can act as a miRNA sponge and repressed the expression of miR-145." (PMID 29221199, 2017). "These outcomes suggest a stable value for UCA1 in the diagnosis of bladder cancer." (PMID 28415640, 2017). "UCA1, located at 19p13.1, was first cloned in bladder carcinoma with a full-length of 1442 bp." (PMID 28209917, 2017). "Thus, the UCA1/Wnt6 pathway represents a potential target for conquering chemoresistance in bladder cancer." (PMID 27713133, 2017). "To further evaluate whether exosomal lncRNA-UCA1 was internalized by bladder cancer cells, we have also evaluated the relative UCA1 expression levels in different bladder cancer cell lines by RT-PCR and qRT-PCR." (PMID 28841829, 2017). "Recent studies have suggested a key role for UCA1 in human cancers, mainly in bladder cancer." (PMID 27046651, 2016). "Furthermore, under hypoxia, UCA1 levels are enhanced in bladder cancer cells compared to controls, and this high level of UCA1 expression is significantly correlated with greater tumor depth and apoptosis escape." (PMID 27686732, 2016). "UCA1 was a long intergenic ncRNA that first discovered in bladder cancer in 2006." (PMID 27517147, 2016). "And the UCA1 could be as a predictive biomarker for bladder cancer in urine samples or lung cancer in plasma, respectively." (PMID 26949706, 2016). "Another study investigated on the function of UCA1 in hypoxic bladder cancer, revealing that UCA1 could function as a HIF-1α-targeted lncRNA to enhance bladder cancer cell invasion." (PMID 27517147, 2016). "UCA1 is a lncRNA reported to promote cell proliferation in both breast cancer and bladder cancer." (PMID 26812883, 2016). "For example, UCA1 is upregulated in the blood of patients with advanced bladder cancer after cisplatin-based combination chemotherapy, suggesting that UCA1 may be used to predict the outcome of chemotherapy for bladder cancer." (PMID 27189224, 2016). "It has recently been shown that lncRNA UCA1 increases the chemoresistance of bladder cancer." (PMID 27977766, 2016). "UCA1 promoted glucose consumption and lactate production in bladder cancer cells, indicating that the UCA1 might be important in providing the energy needed for heart." (PMID 26949706, 2016). "Interestingly, circulating UCA1, including blood and urine, can also be detected in bladder cancer patients." (PMID 27189224, 2016). "UCA1 was found to promote tumorigenicity, with invasive potential in bladder cancer." (PMID 27517147, 2016).
bladder cancer (continued). "On the other hand, some studies have shown that aerobic glycolysis could be promoted by UCA1 in bladder cancer cells by targeting miR-16 and up-regulating hexokinase-2, thus affecting their malignant potential." (PMID 27517147, 2016). "Moreover, in bladder cancer cells the UCA1 lncRNA promotes glutamine metabolism through its sponge function over miR-16, allowing the expression of GLS2, enzyme that participates in the hydrolysis of glutamine to glutamate." (PMID 27551267, 2016). "Between October 2009 and December 2011 the UCA1 test was performed on collected urine samples from 162 patients divided into screening and follow-up groups, based on the absence or presence of prior bladder cancer." (PMID 26191476, 2015). "Several groups have reported that UCA1 is highly expressed in bladder cancer, breast cancer, colorectal cancer, etc., suggesting that UCA1 may serve as a biomarker for the diagnosis of these cancers." (PMID 25760077, 2015). "Moreover, UCA1 enhances bladder cancer cell proliferation and metastasis through PI3K, Wnt or Akt signaling pathway." (PMID 25760077, 2015). "Furthermore, upregulated UCA1 has been shown to promote resistance to cisplatin-based chemotherapy in bladder cancer cells." (PMID 26191476, 2015). "The authors found that UCA1 could serve as a potential biomarker for bladder cancer since it is specifically highly expressed in bladder cancer." (PMID 24993775, 2014). "Knockdown of UCA1 increased Akt expression and activity in bladder carcinoma cells." (PMID 24312245, 2013). "We have previously demonstrated that UCA1 can promote cell growth and invasion in bladder cancer." (PMID 24069250, 2013). "Further analysis of this site by gel shifting, chromatin immune precipitation (ChIP), and co-transfection experiments showed that transcription factor Ets-2 directly bound to the UCA1 promoter region and stimulated UCA1 promoter activity in bladder cancer cells." (PMID 24069250, 2013). "Many studies suggested that UCA1 may act as a molecular marker of bladder cancer because of its excellent specificity and sensibility." (PMID 24069250, 2013). "Furthermore, UCA1 regulated the cell cycle through CREB in the PI3K-AKT dependent pathway in bladder cancer." (PMID 24006935, 2013). "Taking into account the anti-apoptosis function of Ets-2, our data suggested that Ets-2 regulates apoptosis process by regulating the expression of UCA1, moreover UCA1 may be involved in the activation of Akt signaling pathway by Ets-2 in bladder cancer cells." (PMID 24069250, 2013). "The CREB1 is involved in the UCA1-mediated cell cycle distribution of bladder cancer." (PMID 23843741, 2013). "Ets-2 can influence bladder cancer cell apoptosis by regulating the expression of UCA1." (PMID 24069250, 2013). "To test whether Ets-2 regulates Akt pathway through UCA1, we used another bladder cancer cell line BLS-211, which lacks of UCA1 gene expression and it is derived from the same patient as BLZ-211." (PMID 24069250, 2013). "In addition, overexpression of UCA1 could reduce intracellular ROS levels and protect bladder cancer cells from oxidative toxicity." (PMID 37127605, 2023). "Furthermore, UCA1 was reported to be involved in gemcitabine resistance in bladder cancer." (PMID 36499136, 2022). "Evenly, knockout UCA1 bladder cell lines displayed a reduction of cellular periphery and diminished the capacity of maligned cells to spread out through other tissues and therein metastasize, suggesting that UCA1 can be used as potential therapeutic target in bladder cancer prognosis." (PMID 35447891, 2022). "Urothelial cancer-associated 1 (UCA1) was highly expressed in bladder cancer and regulated the cAMP response element-binding protein, chromatin remodeling factor, phosphoinositide 3-kinase, protein kinase B, and Wnt pathways, to promote bladder cancer cell proliferation." (PMID 36185445, 2022).
bladder cancer (continued). "UCA1 has been shown to have high sensitivity for the T2-T4 stage of bladder cancer, suggesting that UCA1 may be considered a marker for the better prognosis of bladder cancer." (PMID 36685879, 2022). "Furthermore, long non-coding RNA UCA1 is associated with mTOR-mediated glucose consumption and lactate production in 5637 human bladder carcinoma cells, although no direct interaction between mTOR and UCA1 was demonstrated." (PMID 33466735, 2021). "Thus, UCA1/Wnt6 pathway was a potential target for bladder cancer resistance." (PMID 32759948, 2020). "Besides bladder cancer, oncogenic functions of lncRNA UCA1 were also identified in other cancers like breast cancer, colorectal cancer, esophageal squamous cell carcinoma, gastric cancer, hepatocellular carcinoma, melanoma, ovarian cancer, and tongue squamous cell carcinoma." (PMID 31695578, 2019). "Our in vitro results also showed that UCA1 promoted chemo-resistance, which was consistent with studies in bladder cancer, and the rescue experiments showed that the effects of UCA1 on the chemoresistance of glioma may be associated with the modulation of Wnt/β-catenin signaling." (PMID 31596734, 2019). "Both in vitro and in vivo studies demonstrated that overexpression of UCA1 increased proliferation, migration, invasion and chemoresistance of bladder cells; antagonized cell apoptosis induced by cisplatin and promoted tumorigenicity of human bladder carcinoma cells." (PMID 29719633, 2018). "Additionally, it has been proposed that the oncogenic role of UCA1 may be related to glucose metabolism in bladder cancer." (PMID 35540445, 2018). "Urine UCA1 has higher diagnostic accuracy for bladder cancer detection in non-Chinese persons than in Chinese persons, indicating that ethnicity may be one of the causes of heterogeneity." (PMID 28415640, 2017). "Notably among the known ones, UCA1 has been reported to promote the growth and metastasis of lung cancer, tumor proliferation and 5-fluorouracil resistance of colorectal cancer, and tumor growth of breast cancer and bladder cancer." (PMID 29137177, 2017). "Likewise, UCA1 expression levels were higher in cisplatin-resistant bladder cancer cells." (PMID 27713133, 2017). "Also, miR-1 has been shown to suppress lncRNA UCA1 expression in bladder cancer cells." (PMID 28969100, 2017). "In addition to involvement in glucose metabolic processes, UCA1 also could promote cell proliferation and inhibit cell apoptosis in bladder cancer." (PMID 26949706, 2016). "Our analysis confirmed the novel function of UCA1 in bladder cancer and provided another potential mechanism that UCA1 may compete with miR-143 to regulate the expression of MMP13 and PTGS2, both of the coding genes were identified here as dysregulated but lack fully elucidation in bladder cancer." (PMID 27863388, 2016). "In addition, UCA1 promoted glycolysis by upregulating hexokinase 2 in bladder cancer cells." (PMID 27009634, 2016). "In addition, it should be concerned that the UCA1 was highly expressed in many cancers such as bladder cancer and lung cancer and could be as predictor biomarker for those cancers." (PMID 26949706, 2016). "Besides the specificity, the UCA1 could be detected in freshly voided urine samples or plasma and be as a predictive biomarker for bladder cancer or lung cancer, respectively." (PMID 26949706, 2016). "In addition, miR-1 plays a tumor suppressive role via downregulating UCA1 in bladder cancer and UCA1 participates in cancer cell glucose metabolism through the cascade of mTOR-STAT3/miR143-hexokinase 2 (HK2), indicating a positive interaction between UCA1 and miRNAs in cancer cells." (PMID 25760077, 2015). "Through analyzing the RIP-seq dataset and GEO database,we identified UCA1 as an interaction partner of IGF2BP3, which was initially recognized as a promoter of bladder cancer." (PMID 38760723, 2024). "However, whether UCA1 plays a role in purine metabolism in bladder cancer is unknown." (PMID 37215997, 2023).